ZNF774 (zinc finger protein 774)
Description:
May be involved in transcriptional regulation.
Synonyms: MGC75360
Tractability: No criterion of Open Targets' tractability assessment is met for any kind of drug.
Gene: Protein-coding gene on chromosome 15 (90,352,284 to 90,369,146, forward strand). Ensembl gene ENSG00000196391.
Subcellular location: Nucleus
Subcellular location (Human Protein Atlas): Intermediate filaments; Cytosol
Pathways (Reactome):
Gene expression (Transcription): Generic Transcription Pathway
Gene Ontology:
Molecular function: protein binding; DNA-binding transcription factor activity, RNA polymerase II-specific; RNA polymerase II cis-regulatory region sequence-specific DNA binding
Biological process: regulation of transcription by RNA polymerase II
Cellular component: intermediate filament cytoskeleton; nucleus
Genetic constraint (gnomAD): Loss-of-function variants: 10 observed, 10.08 expected, observed/expected ratio (o/e) 0.99, 90% interval 0.61 to 1.64. The upper end of that interval is the gene's LOEUF score, 1.64, which puts it in group 6 of 6, group 1 being the genes least tolerant of losing a copy. Missense variants: 596 observed, 615.82 expected, observed/expected ratio (o/e) 0.97, 90% interval 0.9 to 1.04. Synonymous variants: 195 observed, 224.47 expected, observed/expected ratio (o/e) 0.87, 90% interval 0.77 to 0.98.
Homologues: Orthologues: chimpanzee ZNF774 (99% identical), macaque ZNF774 (97% identical). Paralogues in human: ZNF572 (44% identical), ZKSCAN7 (43% identical), ZNF287 (41% identical), ZNF852 (41% identical), ZNF214 (40% identical), ZNF527 (39% identical), ZNF34 (39% identical), ZNF416 (37% identical), ZNF530 (37% identical), ZNF17 (37% identical), ZNF285 (37% identical), ZNF768 (37% identical), and 38 more.
Diseases named in the same sentence as ZNF774 in open-access papers:
ZNF774 is named in the same sentence as 5 diseases in open-access papers, as found by Europe PMC text mining. Sharing a sentence is not in itself a finding about the gene and the disease. The quoted sentences say what the papers report.
COVID-19 (1 paper, 2024). A disease caused by infection with severe acute respiratory syndrome coronavirus 2. "We also observed a suggestive association with rs2601183 in chromosome 15, which is located between ZNF774 and IQGAP1 (allele-G OR = 1.20, 95% CI = 1.12–1.29, p=6.11 × 10–8), which has not yet been reported in any other GWAS of COVID-19 to date." (PMID 39361370, 2024).
neurodevelopmental disorder (2 papers, 2025 to 2026). A behavioral and cognitive disorder with onset during the developmental period that involves impaired or aberrant development of intellectual, motor, or social functions. "The top candidate genes include both genes previously implicated in neurodevelopmental disorders (e.g., ZNF774 and DNAH3) and genes not previously reported but with strong evidence of being involved in neurodevelopmental phenotypes." (PMID 40386381, 2025).
neurological disorders (1 paper, 2025). "ZNF774, another zinc finger protein, is linked to cell growth and neurological disorders when its function is disturbed." (PMID 40141456, 2025).
ZNF774 also shares sentences with these, for which no sentence is quoted: cancer (1 paper); tumor (1).